SSTR2 (somatostatin receptor 2)
Diseases named in the same sentence as SSTR2 in open-access papers (continued):
Sharing a sentence is not in itself a finding about the gene and the disease.
insulinomas (19 papers, 2014 to 2026). "Insulinomas in particular exhibit receptors such as the growth inhibitory receptor 2 (SSTR2) and the glucagon‐like peptide‐1 receptor (GLP‐1 receptor), with over 90% of these tumors expressing the GLP‐1 receptor." (PMID 39935661, 2025). "As insulinomas are known to express SSTR2, SSTR2 agonists such as octreotide and lanreotide have not only been shown to reduce hypoglycemia but also assist with tumor regression." (PMID 40648766, 2025). "Targeted therapy using somatostatin class mimics for SSTR2 to control hormone production is a first-line medicine treatment for most subtypes, with insulinomas excepted." (PMID 37568572, 2023). "In contrast, aggressive insulinomas preferentially express somatostatin receptor subtype 2 (SSTR2) instead of GLP-1R, and, in such cases, SSTR-SPECT scans may be utilized." (PMID 40648766, 2025). "SSTR2 seems to be predominantly expressed also in the case of malignant insulinoma, although this did not predispose to a successful octreotide therapy." (PMID 39329930, 2024). "A more recent insulinoma cell line from a WD tumor, NT-3, has shown promise as an accurate representation of mature beta cells, and has already drawn extensive preclinical research with SSTR2 treatments." (PMID 37568572, 2023). "Contrary to benign insulinomas malignant insulinomas more often express SSTR2 than GLP-1R." (PMID 31951592, 2020). "Loss of SSTR2 expression on insulinoma cells has also been described; however, we do not feel this is a plausible explanation in our patient due to confirmed high SSTR expression on SSTR imaging repeatedly on several occasions." (PMID 25755880, 2015). "In contrast to benign insulinoma, malignant or metastatic insulinoma often lack GLP-1 receptor while overexpressing SSTR-2, making them potentially suitable for SSTR-2 based PRRT." (PMID 35659779, 2022). "Our data indicate that, in contrast to benign insulinomas, malignant insulinomas often lack GLP-1 receptors but express SSTR2." (PMID 31951592, 2020). "Of the five subtypes of SSTRs (named SSTR1–5), SSTR2 and SSTR5 are most commonly expressed in insulinomas (∼70%)." (PMID 25755880, 2015). "The inadequate control of insulin secretion by somatostatin analogs is probably a consequence of the low expression of SSTR2 and SSTR5 in insulinomas, which also explains the reason for the low percentage of SPECT scintigraphy-positive tumors." (PMID 25298880, 2014). "Besides these options, INS‐1832/13 rat insulinoma cell lines, mouse insulinoma 6 (MIN‐6) cell lines), and Cellosaurus beta‐TC‐3 (βTC3) cell lines are commonly employed, and SSTR2 is usually expressed in these cell lines." (PMID 40145271, 2025). "To evaluate whether re-expression of SSTR2 in another cell line would be able to sensitize cells to octreotide, we overexpressed the GFP-tagged rat SSTR2 in the rat insulinoma cell line RIN-1038." (PMID 29681888, 2018). "A partial response with single-digit nanomolar IC50 was observed in RIN-1038 rat insulinoma cells transfected with rat SSTR2-GFP yet not in the parental wild-type cells, demonstrating the principle feasibility of this approach in a neuroendocrine cell line." (PMID 29681888, 2018). "The detection rate of 111In-DTPA-octreotide scintigraphy is better for gastrointestinal NETs with sensitivity ranging from 80 to 100 %, but lower for insulinomas with sensitivity 20 to 60 %, as not all insulinomas express SSTR2." (PMID 26911576, 2016). "Due to small size and/or lack of SSTR2 expression in 50 % of insulinoma, SSTR-related imaging plays a minor role than morphological imaging." (PMID 25038902, 2014). "A testament to the importance of SSTR2 in the case of NET treatment is the case of advanced insulinomas, which typically have a low SSTR2 expression and are therefore less or non-responsive to octreotide treatment, demonstrating that SSTR expression is a critical factor in treatment effectiveness." (PMID 39329930, 2024).
insulinomas (continued). "Finally, although there are no established individual models for pNENs, canine insulinomas mimic the sporadic, long-term development nature of humans and have similar mutations including MEN1, ATRX, and in SSTR2 expression." (PMID 37568572, 2023). "Transcriptional upregulation of SSTR2 has also been shown with physiological factors such as insulin and growth hormones in liver cells of rainbow trout and it has been correlated with octreotide-induced overexpression of miR-16-p in INS-1 rat insulinoma NET cell line." (PMID 33435224, 2021).
pituitary tumor (19 papers, 2015 to 2025). A benign or malignant neoplasm affecting the pituitary gland. "Patients with untreated CD are by definition characterized by hypercortisolism that causes low SSTR2 expression levels in the pituitary tumor tissue, negatively affecting the response to OCT treatment." (PMID 40488558, 2025). "In fact, in vivo pituitary tumors expressing low levels of SSTR2 and high levels of SSTR5 showed a greater therapeutic response with the use of pasireotide versus octreotide." (PMID 39064468, 2024). "Sstr2 agonists are used to suppress excess growth hormone (GH) secretion in functional pituitary tumors." (PMID 36965619, 2023). "Previous studies support the presence of other SSTR subtypes in pituitary tumours in addition to SSTR2." (PMID 38203605, 2023). "The cytotoxic effect of SSTR2 selective analog BIM23120 has been observed in human pituitary tumours." (PMID 38203605, 2023). "For example, in the mouse pituitary tumor cell line AtT20, it was recently shown that extended treatment of cells with Sstr2 agonists leads to receptor degradation via the lysosome." (PMID 36965619, 2023). "Adrenocorticotropic hormone (ACTH)-secreting pituitary tumors mainly express somatostatin receptor 5 (SSTR5) since SSTR2 is downregulated by the elevated levels of glucocorticoids that characterize patients with Cushing’s disease (CD)." (PMID 37435448, 2022). "The importance of FLNA in SSTR2 regulation in GH-secreting pituitary tumors has recently been examined." (PMID 26733942, 2015). "SSAs stimulate p27 expression and inhibit the MAPK pathway in pituitary tumors by binding to SSRT2 and SSRT5.Studies have found that SSTR2 and SSTR5 also express in TSHoma cells, suggesting that SSAs can be used to treat TSHoma." (PMID 37587420, 2023). "Together, these data suggest that relacorilant-mediated upregulation of SSTR2 provides more targets for somatostatin and somatostatin analogs, which can lead to tumor shrinkage in ACTH-secreting pituitary tumors." (PMID 35058882, 2021). "In addition, it was shown that increased activity of SSTR2 induced an attenuation of GH synthesis in GH3 rat pituitary tumor cells and STTR3 activation mediated transcriptional repression of gh in GC pituitary tumor cell line." (PMID 38994081, 2024). "Pituitary MRI revealed a pituitary tumor with mild 68Ga-DOTATATE uptake, which may be related to small lesions and decreased SSTR2 expression." (PMID 36042606, 2022). "Patients affected by other types of PBTs such as pituitary tumors may benefit from PRRT with radiolabeled somatostatin analogs, especially GH and TSH tumors (as we showed, these tumors express high levels of SSTR2)." (PMID 34577572, 2021). "Low expression of β-arrestin 1, but not β-arrestin 2, in GH- and PRL-secreting pituitary tumors correlates with a reduced recycling rate of SSTR2 and better SS analogs response in terms of GH suppression, both in vitro and in vivo." (PMID 26733942, 2015). "Moreover, the results of the present study demonstrate that the negative modulation of miR-375, by positively impacting on SSTR2 expression in human and murine corticotroph pituitary tumor cell models, potentiates the OCT antiproliferative effect." (PMID 40488558, 2025). "Indeed, in some neuroendocrine and pituitary tumors, a truncated or spliced SSTR5 variant blocks SSTR2 signaling, which explains the lack of effect of SST analogues in these tumors, even in the presence of normal SSTR2 expression." (PMID 31569719, 2019). "The lack of SSTR2 imaging or immunohistochemical analysis of SSTR2 expression before and after relacorilant treatment is another limitation for patient cases 3 and 4; however, SSTR2 imaging is not part of the standard diagnostic evaluation of ACTH-secreting pituitary tumors." (PMID 35058882, 2021).
pituitary tumor (continued). "Finally, as somatostatin receptor genes (SSTR2, 3 and 5) are putative targets for miR-383, and STAT3 has been proposed as a promising target candidate for pituitary tumor immunotherapy, our results might also suggest that miR-383 could be a therapeutic target in corticotroph PitNETs." (PMID 32545591, 2020).
adenoma (17 papers, 2013 to 2025). A neoplasm arising from the epithelium. "Lim and Fleseriu (2022) further emphasized that factors such as sparsely granulated adenomas, low SSTR2 status, and genetic mutations can predict resistance to first-generation SSAs, suggesting these patients might be better candidates for pegvisomant or pasireotide treatment." (PMID 40575269, 2025). "In the three prolactin-secreting adenomas studied, the expression of SSTR2 was stronger than that of SSTR5." (PMID 39202532, 2024). "Histologically, it is possible to divide adenomas into two different types, densely and sparsely granulated ones; the first type, expresses SSTR2 much more than the latter and is thus more responsive to treatments with SSTR ligands." (PMID 39329930, 2024). "As expected, we confirmed that low-grade SSTR2 expression (i.e., score 0–1 vs. 2–3) was significantly more frequent among resistant adenomas (40.9 vs. 14.3%, R-SRL vs. S-SRL, p = 0.024)." (PMID 36614826, 2022). "Higher expression of SSTR2 was observed in the microfollicular adenoma compared to the surrounding healthy tissue, with predominant localization in the endothelial cells and at the secretory pole of the thyroid epithelial cells in contact with blood vessels." (PMID 35437615, 2022). "The IGF‐1 per cent reduction after 3 and 6 months of SSAs treatment was also significantly lower when we compared adenomas with low (score 1) and moderate/high (scores 2 and 3) SSTR2 expression (P = 0.001 and 0.003, respectively)." (PMID 29266696, 2018). "Although previous studies have suggested that SSTRs other than SSTR2 are involved in this type of adenomas, studies involving other SST analogues like SOM230 should be further evaluated, as high expression levels of SSTR3 in these adenomas are of great relevance." (PMID 38203605, 2023). "Somatostatin receptor subtype 2 (SSTR2) was found to be increased in adenomas with respect to normal pituitaries while it was decreased in patients non-responding to treatment with long-acting Somatostatin analogues (SSAs) with respect to responders and was involved in GH secretion suppression." (PMID 34484116, 2021). "In another study, 15 SCAs demonstrated greater immunoreactive scores for SSTR2 compared with null cell adenomas (defined in that study as hormone-, SF1-, and PIT1-negative samples; n = 10) and greater immunoreactive scores for SSTR5 compared with SGAs (n = 110)." (PMID 30020466, 2019). "Moreover, SSTR2 expression was significantly lower in adenomas that were exposed to octreotide prior to surgery than those that did not receive pretreatment." (PMID 28396686, 2017). "In Cushing's disease, ACTH secreting adenomas predominantly express SSTR5 but SSTR2 expression is also seen, which may be involved in the hypercortisolaemia seen in our case." (PMID 24616766, 2013). "However, high expression of somatostatin receptor 2 (SSTR2) was observed in the microfollicular adenoma compared to the surrounding healthy tissue, with predominant localization in the endothelial cells and at the secretory pole of the thyroid epithelial cells in contact with blood vessels." (PMID 35437615, 2022). "Finally, TSH adenomas showed 68 genes that could be regulated by methylation including SSTR2, GRIA2 and LINC01173." (PMID 33168897, 2020). "IHC analysis, using a 12-grade scoring system, with rabbit monoclonal antibodies against SSTR2 and SSTR5, was performed on all adenoma tissues." (PMID 28396686, 2017). "In order to detect the expression pattern of SSTR2 and SSTR5 in the normal pituitary and adenomas from both the DS group and SA group, we performed IHC analysis by using rabbit monoclonal antibodies against these two receptors." (PMID 28396686, 2017). "A previous study from our group also found a lower SSTR2 mRNA expression in NFPA in comparison to somatotropinomas, however, the SSTR3 was similar in these adenoma subtypes." (PMID 24098585, 2013). "Both SSTR2 and SSTR5 were significantly elevated in TSHoma compared to other adenomas." (PMID 39202532, 2024).
adenoma (continued). "In addition to the expression of SSTR2 mRNA, the expression of SSTR5 mRNA may also influence tumor shrinkage by somatostatin analogs against TSH-secreting adenomas." (PMID 39202532, 2024). "Likewise, other studies have suggested that SSTR3 is the predominant SSTR expressed in hormone-negative adenomas and SGAs, both by IHC studies and mRNA levels, and SSTR2 expression was shown to be absent in another cohort of true null cell adenomas." (PMID 30020466, 2019). "In silico analysis evidenced that SSTR2 was a putative target of miR-185 and, intriguingly, miR-185 was upregulated in tumor samples from SSA non-responder adenoma patients with respect to controls while it was downregulated in the SSA responder patients." (PMID 34484116, 2021). "Some other studies, however, have reported greater SSTR2 expression than SSTR3 or SSTR5 in SGAs and hormone-negative adenomas." (PMID 30020466, 2019). "Immunoreactivity for SSTR2 and SSTR5 has been shown to be positive in 89% and 78% of silent thyrotroph adenomas, respectively, a difference that was not significantly different from the hormonally active adenomas." (PMID 30020466, 2019).
small cell lung carcinoma (17 papers, 1999 to 2025). Small cell lung cancer (SCLC) is a highly aggressive malignant neoplasm, accounting for 10-15% of lung cancer cases, characterized byrapid growth, and early metastasis. "A point mutation in the SSTR2 gene has earlier been reported in a human small-cell lung cancer." (PMID 10604740, 1999). "As a consequence, cell lines with higher SSTR2 expression, such as the small cell lung cancer cell line NCI-H69, are often used for SSTR2-directed TRT studies." (PMID 40016527, 2025). "Data presented at the 2018 ASCO meeting showed disease stabilisation of up to 12 weeks in patients with aggressive, advanced, SSTR2-positive small cell lung cancer treated with PEN-221." (PMID 41463450, 2025). "In the evaluation conducted on a human small-cell lung cancer (NCI-H69) xenograft model overexpressing SSTR2, [111In]In-eTFC-01 and [111In]In-DOTA-TATE were compared." (PMID 38775990, 2024). "eSOMA-01 and eSOMA-02 were first labeled with 203Pb, an imaging surrogate of 212Pb, and evaluated in a human small-cell lung cancer (NCI-H69) xenograft model overexpressing SSTR2." (PMID 37513897, 2023). "The small cell lung cancer cell line NCI-H69 was devoid of SSTR1 expression but strongly expressed SSTR2, SSTR3, and SSTR5." (PMID 29282035, 2017). "Indeed, that study further showed that downregulation of SSTR2 leads to increased apoptosis and decreased tumor growth in small cell lung carcinoma." (PMID 35198446, 2022). "The authors concluded that SSTR2 signaling in small cell lung cancer may support tumor growth and maintenance." (PMID 35198446, 2022). "The human small cell lung cancer (SCLC) H69 cell line, used in our studies, expresses SSTR2 in high densities." (PMID 26553049, 2015). "In a mouse model of NET tumor with H69 small cell lung cancer cells, a 14-day treatment with TEM did not increase SSTR2 density on cells, but increased the tumor uptake of 111In-octreotide or LuTate due to increased tumor perfusion of the radiopharmaceutical." (PMID 33435224, 2021).
prostate carcinoma (16 papers, 2009 to 2025). A carcinoma that arises from epithelial cells of the prostate gland. "They reported that prostate cancer displaying loss of SSTR2 is a highly aggressive and proliferative and possible indicator of early metastatic and relapse." (PMID 38203605, 2023). "We have been able to clarify that loss of SSTR2 is strongly linked to an aggressive tumor phenotype and predicts poor prognosis of prostate cancers." (PMID 25010045, 2014). "SSTR2 deficiency in prostate cancer may explain the treatment ineffectiveness of some selective somatostatin analogs." (PMID 33586406, 2021). "Lastly, we show that loss of SSTR2 was linked to metastatic progression of prostate cancers." (PMID 25010045, 2014). "New targets for prostate cancer are currently being studied, such as neurotensin receptor-1 (NTS1), somatostatin receptor-2 (SST2) or chemokine receptor-4 (CXCR4) —suggested to be expressed in prostate cancer in a few small pilot studies." (PMID 37190273, 2023). "High expression of SSTR2 in stromal cells was further proved by the efficient binding of octreotide to the stromal cells of the prostate cancer tissue." (PMID 38203605, 2023). "An index of prostate cancer growth, the Gleason grade is negatively linked with the reduced expression of SSTR2, along with SHP-1, in prostate cancer." (PMID 38203605, 2023). "The only limitation for PRRT in prostate cancer treatment is the lower expression of SSTR2 in prostate adenocarcinoma." (PMID 38203605, 2023). "Most interestingly, in prostate cancer cells SSTR2 is also able to inhibit another feature of cancer metastasis, cell migration." (PMID 25010045, 2014). "Although, the suitability of SSTR2 as a target for gene therapy needs to be evaluated, loss of SSTR2 is strongly linked to invasiveness, early PSA relapse, and metastatic spread in prostate cancer." (PMID 25010045, 2014). "Immunohistochemically detectable cytoplasmic and membranous SSTR2 protein was seen in 44% of our 2,195 interpretable prostate cancer samples." (PMID 25010045, 2014). "About 13% of all analyzed prostate cancers showed moderate to strong cytoplasmic and membranous SSTR2 staining." (PMID 25010045, 2014). "Previous studies had analyzed smaller patient cohorts (14–45 cases) and found highly variable results including lower and higher numbers of “SSTR2-positive” prostate cancers as compared to our data." (PMID 25010045, 2014). "The aim of this study was to clarify prevalence and clinical significance of SSTR2 expression in prostate cancer." (PMID 25010045, 2014). "In prostate cancers highly contradictory results in terms of SSTR2 expression and its consequences have been published over the past years." (PMID 25010045, 2014). "Patients with SSTR2-negative prostate cancers had impaired metastasis-free survival, and metastases of prostate cancers expressed even lower levels of SSTR2 mRNA than primary prostate cancers." (PMID 25010045, 2014). "In total, prostate cancers from 36 patients (62.1%) showed lower SSTR2 expression than their corresponding normal adjacent tissue." (PMID 25010045, 2014). "Normal epithelial prostate cells express SHP-1 and SSTR2, but we report that the levels of expression were diminished or lost for two proteins in advanced prostate cancer with an inverse ratio between protein expression and Gleason grade of tumor." (PMID 19365586, 2009). "Low mRNA expression of SSTR2 was observed in the prostate cancer cell lines PC-3, DU-154 and LNCAp." (PMID 38203605, 2023). "Furthermore, studies have shown the reduced expression of SSTR2, along with SHP-2, in advanced prostate cancer cases, but the molecular mechanism associated with such loss in receptors protein and signalling pathways is not well known." (PMID 38203605, 2023).